SALL2 (spalt like transcription factor 2)
Diseases named in the same sentence as SALL2 in open-access papers (continued):
Sharing a sentence is not in itself a finding about the gene and the disease.
cancer (continued). "SALL2 is a transcription factor that plays key roles in embryonic development, cell growth, programmed cell death, and cancer progression." (PMID 40869218, 2025). "The SALL2 transcription factor is notable for its role in neurogenesis and neurodifferentiation, as well as in many cancers." (PMID 39062462, 2024). "Accordingly, pharmacological inhibition of CK2 with Silmitasertib (CX-4945) restored endogenous SALL2 protein levels in SALL2-deficient breast MDA-MB-231, lung H1299, and colon SW480 cancer cells." (PMID 38493149, 2024). "Overall, our results show that SALL2/Sall2 expression sensitizes cancer cells to Silmitasertib cytotoxicity, indicating that restoration of SALL2/Sall2 function favors cell death in response to CK2 inhibition." (PMID 38493149, 2024). "It is reported that a tRNA‐modifying methylthiotransferase CDKAL1 promotes cancer stem‐like cells (CSC)‐factor SALL2 synthesis by assembling the eIF4F translation initiation complex." (PMID 36786012, 2023). "In summary, our results propose that Sall2 promotes cell migration by modulation of focal adhesion dynamics in a non-cancer context." (PMID 36438565, 2022). "Analyses of expression patterns from cancer samples versus normal samples indicated that SALL2 has differential expression in 16 out of 21 cancer types, most significantly in the brain, colorectal, and testis tissues (p-values)." (PMID 33692826, 2021). "To further investigate SALL2 expression in normal and cancer contexts based on more extensive studies, we used MiPanda server." (PMID 33692826, 2021). "Our work provides insights into SALL2 isoform-specific transcriptional targets and evidence of a conserved TF network relevant to cancer studies." (PMID 33692826, 2021). "Previous studies based on a limited number of samples indicate that the SALL2 gene is highly expressed in the normal brain, testis, thymus, and differentially expressed in some cancers." (PMID 33692826, 2021). "Sall2, another emerging cancer player in the Sall family, binds to the cMyc promoter region and represses cMyc expression." (PMID 32098783, 2020). "However, mechanisms underlying roles of SALL2 related to cancer remain largely unknown." (PMID 29689621, 2018). "Datasets from different types of cancer were used to investigate correlation between SALL2 and CCND1/E1 genes’ expression." (PMID 29689621, 2018). "According to previous data on the role of SALL2 in the proliferation of cancer cells, and with our data on primary MEFs, Sall2−/− iMEFs also showed higher rate of proliferation compared to the Sall2+/+ counterpart." (PMID 29689621, 2018). "SALL2 is identified as one of the candidate drivers for attenuating histological grade promotion, and in preventing cancer progression." (PMID 29689621, 2018). "The Sall2 transcription factor is deregulated in several cancers; however, little is known about its cellular functions, including its target genes." (PMID 26181197, 2015). "SALL2- a member of the Spalt gene family- is a poorly characterized transcription factor found deregulated in various cancers, which suggests it plays a role in the disease." (PMID 24040083, 2013). "Understanding how SALL2 is regulated under different cell scenarios should help to understand its deregulation in cancer." (PMID 24040083, 2013). "The SALL2 P2 promoter (344bp) luciferase reporter was kindly provided by Dr. Thomas Benjamin (Dana Farber, Harvard Cancer Center, USA)." (PMID 24040083, 2013). "In an attempt to understand SALL2 deregulation in cancer, we searched for potential cancer-related transcription factor binding sites in the SALL2 gene." (PMID 24040083, 2013).
cancer (continued). "Similarly, 21.8% of vimentin-positive cells were SALL2-positive in normal tissue, whereas only 1% in cancer tissue showed this positivity." (PMID 40869218, 2025). "SALL2 is downregulated or upregulated in cancer depending on the cancer type and stage." (PMID 38493149, 2024). "Together, our results suggest that CK2-dependent downregulation of SALL2 occurs in cancer cells." (PMID 38493149, 2024). "We propose a new mechanism for reducing SALL2 levels in cancer cells, which may have implications for cancer therapy with CK2 inhibitors." (PMID 38493149, 2024). "Given that SALL2 promotes cell death, we reasoned that the downregulation of SALL2 by CK2 may impact cell survival in cancer cells." (PMID 38493149, 2024). "However, SALL2’s role in cancer is controversial because it is upregulated in Wilms’ tumors, synovial sarcoma, testicular germ cell tumors, oral tongue squamous cell carcinoma, and glioblastoma." (PMID 38493149, 2024). "However, it is important to consider that the SALL2 locus has been reported to undergo LOH in certain types of cancer, likely compromising the efficacy of these combined treatments." (PMID 38493149, 2024). "The apparent controversy on the role of SALL2/Sall2 in the migration of A2780 cancer versus MEFs, a non-cancer cell model, might relate to several reasons." (PMID 36438565, 2022). "Altogether, our analyses suggest that SALL2 has a conserved network of target genes that rely on self-renewal transcription factors and a core of genes important for SALL2-mediated transcriptional regulation in human cancers." (PMID 33692826, 2021). "Increasing studies indicate that SALL2 plays a role in cancer." (PMID 29689621, 2018). "Likely, SALL2 regulation of cyclin D1 and E1 expression is genetic context‐dependent, which could explain the observed inverse correlations in only a subset of cancers." (PMID 29689621, 2018). "Finally, we show that the Sall2/Noxa axis is also important for the cell death response to doxorubicin in Jurkat T cells, supporting the significance of this axis in a cancer cell context." (PMID 26181197, 2015). "Besides its role in neuronal development and neurogenesis, several evidences suggest that SALL2 plays a role in cancer." (PMID 24040083, 2013). "Understanding SALL2 regulation should provide insights about its deregulation in cancer." (PMID 24040083, 2013). "Contradictory, SALL2 is found upregulated in several cancers." (PMID 24040083, 2013). "Thus, therapies combining agents that induce DNA damage with Silmitasertib may promote synergistically SALL2-dependent cancer cell death." (PMID 38493149, 2024).
cancer (continued). "Treatment with Silmitasertib increased the levels of SALL2 in H1299, MDA-MB-231, and SW480 cancer cell lines." (PMID 38493149, 2024). "Thus, PODXL and NRARP may be conserved SALL2 targets across species, tissues, and cancer types." (PMID 33692826, 2021). "Thus, the SALL2-PODXL transcriptional regulation may be necessary for cancer stemness." (PMID 33692826, 2021). "Overexpression of the other four (SOX2, POU3F2, OCT-4, and OLIG1) or five (SOX2, SALL2, OCT-4, POU3F2, and Bmi-1) transcription factors in YB-1 knockout cancer stem cells generated similar results." (PMID 31375149, 2019). "A short E1A SALL2 isoform, lacking DNA binding domain and most Zinc finger motifs, is also deregulated in cancer contexts." (PMID 36438565, 2022). "Considering that no previous studies show a direct role of SALL2/Sall2 in cell migration in a non-cancer context, our results in iMEFs are the first to demonstrate that Sall2 plays a positive role in promoting cell migration." (PMID 36438565, 2022). "Contrary to the cancer context, we observed higher levels of PTEN in Sall2−/− cells, which supports PTEN as an alternative or complementary mechanism in the Sall2-mediated FAK activation." (PMID 36438565, 2022). "SALL1, SALL2, and SALL4 cancer-related isoforms have been reported." (PMID 34944911, 2021). "Taken together, among the SALL2 target genes functionally related in GBM, PODXL might also have a functional relationship with SALL2 in other cancer types." (PMID 33692826, 2021). "However, the cellular location and significance of the inactive SALL2 protein in cervical and other HPV-related cancers require further investigation." (PMID 34944911, 2021). "In GBM cell population, SOX2, along with POUF3F2, SALL2 and OLIG2, forms a group of core transcription factors that triggers an epigenetic effect in cancer cells leading to a formation of tumor propagating cancer stem-like cells, making SOX2 a good candidate for cancer stem cell marker." (PMID 32092088, 2020). "Furthermore, simultaneous expressions of YB-1 and the other four (SOX2, POU3F2, OCT-4, and OLIG1) or five (SOX2, SALL2, OCT-4, POU3F2, and Bmi-1) transcription factors in YB-1 knockout cancer stem cells restored the stemness of YB-1 knockout cancer stem cells." (PMID 31375149, 2019). "The detailed mechanisms of actions for MYB family in cancer development involving other transcription factor partners, such as SALL2, XBP1, and POU2F1, are still not clear." (PMID 24639887, 2014). "Analysis of data in The Cancer Genome Atlas shows negative correlations between SALL2 and c-MYC expression in four common solid tumor types." (PMID 23029531, 2012). "Breast MDA-MB-231 and colon SW480 cancer cells were selected based on the fact that there is no reported deletion or transcriptional silencing of the SALL2 gene -as opposed to SK-OV-3 and HL-60 cell lines, suggesting that the selected cells have the capacity to generate the protein product." (PMID 38493149, 2024). "SALL2 deregulates in various cancer types, but its role in the disease is not entirely understood." (PMID 36438565, 2022). "Finally, cancer data analyses show negative correlations between SALL2 and G1‐S cyclins’ mRNA levels in several cancers." (PMID 29689621, 2018). "We previously identified SALL2 as a novel interacting protein of neurotrophin receptors and showed that it plays a role in neuronal function, which does not necessarily explain why or how SALL2 is deregulated in cancer." (PMID 24040083, 2013). "Therefore, identifying differential functions of SALL2/Sall2 isoforms may resolve its contradictory role in cell migration between cancer and non-cancer cells." (PMID 36438565, 2022).
cancer (continued). "Current reviews on SALL proteins’ role in cancer are available; however, they are only focused on SALL4 or SALL2, lacking an integrated view of the SALL family." (PMID 34944911, 2021). "Current reviews of SALLs have focused only on SALL2 or SALL4, lacking an integrated view of the SALL family members in cancer." (PMID 34944911, 2021). "The expression of a different SALL2 isoform in A2780 and ESCC cancer cells may explain the contradictory results but was not established." (PMID 36438565, 2022). "In addition, the correlation between SALL2 and CCND1 expression was ambiguous, finding positive and negative correlations depending on the cancer type." (PMID 29689621, 2018).
infection (1 paper, 2017). The state of being infected such as from the introduction of a foreign agent such as serum, vaccine, antigenic substance or organism. "The number of A2780 cells transfected with SALL2 siRNA in the G0/G1 phase was lower than that of the cells in the Scramble group (P < 0.05) for 48 h (56.94% G0/G1 phase cells in Scramble group vs. 48.87% in A2780 cells at 48 h after siRNA infection)." (PMID 29228922, 2017). "The A2780 cells transfected with SALL2 siRNA for 48 h exhibited a lower extent of apoptosis than did the cells of the Scramble group (P < 0.05) (22.3% early apoptotic cells and 4.5% late apoptotic cells in Scramble group vs. 16.2% and 2.6% in A2780 cells at 48 h after siRNA infection)." (PMID 29228922, 2017).
SALL2 also shares sentences with these, for which no sentence is quoted: testicular cancer (4 papers); acute myeloid leukemia (3); acute promyelocytic leukemia (1); adenocarcinoma (1); Anophthalmia (1); brain cancer (1); brain disorder (1); cellulitis (1); Duane-radial ray syndrome (1); gastrointestinal tumours (1); hepatoblastoma (1); liver cancer (1); microphthalmia (1); neuroblastoma (1); Okihiro syndrome (1); ovarian tumours (1); prostate carcinoma (1); rectal adenocarcinoma (1); stomach adenocarcinoma (1); stomach cancer (1); testis tumors (1); tongue squamous cell carcinoma (1).